TNF (tumor necrosis factor)
Diseases named in the same sentence as TNF in open-access papers (continued):
Sharing a sentence is not in itself a finding about the gene and the disease.
Crohn disease (continued). "We further demonstrated that GSK2256294, a clinical EPHX2i, reduced the production of IL2, IL12p70, IL10 and TNFα in both ulcerative colitis and Crohn's disease patient-derived explant cultures." (PMID 31002701, 2019). "All the CD patients were being treated with medications, including mesalazine, corticosteroids, azathioprine, and TNF antagonist, and in most cases, the disease was inactive based on the Crohn’s disease activity index (average CDAI, 71.1)." (PMID 31767028, 2019). "Biological intervention for Crohn's Disease (CDs) patients, mainly using anti-TNF antibodies, is often an efficient therapeutic solution." (PMID 31737635, 2019). "In regard to IL-1β and TNF-α regulation by calcitriol, it has been demonstrated that this hormone enhanced muramyl dipeptide-induced TNF-α production in monocyte-derived dendritic cells from Crohn's disease patients." (PMID 31093512, 2019). "Antibodies towards TNFα have become fundamental in the treatment of both ulcerative colitis and Crohn’s disease since the first reports of patients entering remission after treatment with the anti-TNFα antibody infliximab in 1997." (PMID 30813280, 2019). "Expression of pro-inflammatory cytokines: IL-1α, IL-1β, TNFα, and IL-15 were increased in IL-1rn-/- mice, and these results are in agreement with those obtained from patients with Crohn's disease." (PMID 31191826, 2019). "Certain TNF-α and IL-10 haplotypes were associated with a higher production of TNF-α and IL-10 in Crohn’s disease and ulcerative colitis, possibly explaining the differences observed in baseline target concentrations and response observed in patients." (PMID 31817205, 2019). "The blockage of TNF with anti-TNF antibody constructs (for Crohn's disease) and anti-IL-1 (diseases with inflammasome activation) has been shown to reverse the hearing loss." (PMID 31781229, 2019). "Plasma concentration of TNF-α is higher in patients with Crohn’s disease (CD) than healthy controls (HC) and correlates positively with disease activity." (PMID 30765731, 2019). "Infliximab (IFX) is a TNF-α inhibitor approved for the induction and remission of Crohn’s disease (CD)." (PMID 30286108, 2018). "In this review, we focus on the use of anti-TNF therapy in Crohn’s disease, its mechanism of action, role and future directions in therapeutic use." (PMID 30065229, 2018). "Monoclonal antibodies against tumor necrosis factor alpha (TNFα) have significantly improved the therapeutic options for Crohn’s disease patients." (PMID 29364909, 2018). "The efficacy of TNF inhibitors has been demonstrated in a variety of autoimmune and granulomatous inflammatory diseases such as Crohn's disease, sarcoidosis, and rheumatic diseases." (PMID 30279689, 2018). "In fact, a small study where Crohn’s disease patients with stenotic disease were treated with IFX to evaluate the effect of anti-TNF on strictures, had to be terminated prematurely because of high need for surgery." (PMID 29364909, 2018). "In summary, our findings demonstrate that in patients with Crohn’s disease, anti-TNFα administration reduces visceral sensitivity and improves implicit measures of cognition consistent with an improved sense of wellbeing." (PMID 29518097, 2018). "In patients with Crohn’s disease, anti-TNFα administration reduces visceral sensitivity and improves implicit cognitive-affective biases linked to alterations in limbic (amygdala) function." (PMID 29518097, 2018). "In studies in Crohn’s disease with human IL-10 treatment, higher dose IL-10 treatment led to elevated levels of inflammatory mediators, specifically IFNγ and TNFα." (PMID 30249047, 2018). "Butyrate is known to decrease TNF production through NFκB inhibition, as stated in a study done among patients with Crohn disease." (PMID 30112005, 2018). "Immunotherapies using neutralizing antibodies targeting TNF-α, IL-12/IL-23 subunit p40, or integrins have been successfully used to treat moderate-to-severe Crohn's disease (CD)." (PMID 30140166, 2018).
Crohn disease (continued). "Single nucleotide polymorphism in the IL26 gene results in reduced bacterial killing, elevated concentration of pro-inflammatory cytokines, and increased consumption of anti-TNF antibodies in Crohn’s disease patients with translocated bacterial DNA." (PMID 29967613, 2018). "A recent study in Crohn’s disease patients has shown changes in the microbiota composition after TNF-α inhibitor (adalimumab) treatment, with recovery of phylogroups (Firmicutes, Bacteroides and Actinobacteria) and decrease of E. coli during treatment." (PMID 29615661, 2018). "By contrast, treatment with a soluble TNF receptor, which was ineffective in treating Crohn’s disease, binds soluble TNF, which the authors propose blocks the ability of TNF to promote mucosal healing." (PMID 29922293, 2018). "The recombinant anti-TNF-α antibody infliximab, which blocks both soluble and membrane TNF-α, demonstrated clear clinical efficacy in the treatment of Crohn’s disease and RA." (PMID 29541073, 2018). "TNF-α is overexpressed in patients with colitis ulcerosa and Crohn’s disease, and the degree of mucosal inflammation is positively correlated with chemokine secretion patterns." (PMID 30518097, 2018). "In fact, infliximab, a monoclonal antibody to tumor necrosis factor (TNF)-α, reduces bone loss in patients with Crohn’s disease." (PMID 30071694, 2018). "Anti-TNF treatment currently represents a central treatment modality in Crohn’s disease and can be improved by rapid dose escalation and the use of combination therapy." (PMID 30065229, 2018). "The symptoms observed in Crohn's disease result from an altered intestinal immune system response that triggers the excessive release of cytokines such as TNF-α, IFN-γ, IL-12, IL-13, and IL-17, secreted by Th1 cells." (PMID 30254638, 2018). "The second study, which compares a combination therapy to monotherapy anti-TNF in the pediatric Crohn’s Disease, leverages the ImproveCareNow network to recruit participants who are starting anti-TNF treatment." (PMID 29351763, 2018). "We aimed to assess the effects of anti-TNFα therapy on the central processing of self-attribution biases and visceral afferent information in patients with Crohn’s disease." (PMID 29518097, 2018). "Adalimumab is an antitumour necrosis factor (TNFα) biologic therapy indicated for thetreatment of Crohn’s disease (CD)." (PMID 31294360, 2018). "This body of knowledge explains why anti-cytokine therapies based on TNF-specific blocking agents represent an important cornerstone of medical therapy in both Crohn’s disease and ulcerative colitis." (PMID 30559669, 2018). "Anti-TNF (tumour necrosis factor) therapy was approved for use in Crohn’s disease in 1998, and has changed the paradigm of treatment, leading to improved rates of response and remission in patients." (PMID 30065229, 2018). "Fatigue was significantly related to female sex, Crohn’s disease, joint disorders, body mass index (BMI), psychological tests, thiopurine use, and anti-TNF treatment." (PMID 28749985, 2017). "Existing clinically available anti-TNF therapies (e.g., adalimumab, infliximab, and certolizumab) are an effective therapy for these pateints with remission seen for Crohn’s disease and other related conditions." (PMID 29312310, 2017). "It is worth noting that TNF-α is commonly used to treat Crohn’s disease, and in this present model TNF-α and other cytokines have been shown to be upregulated." (PMID 28493993, 2017). "For instance, the creeping fat in patients with Crohn’s disease (CD) has been referred to as the inflammatory mesenteric fat hypertrophy mediated by a rise in proinflammatory adipokines, including TNF-α, TWEAK, leptin and IL-1β." (PMID 28425943, 2017). "TNF-α is an extremely important cytokine in the treatment of Crohn's disease and UC, and investigations have been underway regarding the possibility of using ADM to treat Crohn's disease." (PMID 28210268, 2017).
Crohn disease (continued). "Anti-TNF agents are effective as both induction and maintenance therapies in moderate-to-severe Crohn's disease in adults, including patients with fistulas." (PMID 29204155, 2017). "In patients with active Crohn’s disease, colonic biopsies cultured with glutamine and L-Arg demonstrate decreased TNF-α production and decreased expression of the NF-κB p65 protein." (PMID 28334039, 2017). "In contrast, anti-TNF biologicals, particularly etanercept fail in Crohn's disease possibly due to ineffective targeting of mTNF that drives localised pathology." (PMID 28197335, 2017). "The most frequent disease requiring TNF antagonist therapy was RA (36.9%), followed by AS (24.8%), Crohn’s disease (CD) (20.1%), ulcerative colitis (UC) (11.4%), and “others” (6.8%)." (PMID 28743918, 2017). "All patients developed typical manifestations of Crohn’s disease or ulcerative colitis, where monoclonal TNFα antibodies or DMARDS were required to gain disease control (for comparison)." (PMID 28288653, 2017). "As a matter of fact, high levels of TNFα are thought to induce enterocytes apoptosis and supplementation with anti‐TNF antibodies is of important clinical benefit to patients suffering from Crohn's disease." (PMID 28474815, 2017). "One research group has found a reduction in the bacterial species Firmicutes phylum in patients affected by relapsing Crohn’s disease as compared to clinically stable patients with administration of anti-TNFα agents." (PMID 29387048, 2017). "In our series, when all patients with Crohn's disease and ulcerative colitis treated with anti-TNF were analyzed, serum prohepcidin was significantly decreased before W6 administration compared with baseline levels at T0." (PMID 28191453, 2017). "This increase in TNF was thought to protect against the onset of intestinal inflammation in the SAMP mouse model of Crohn’s disease-ileitis via local stimulation of the epithelial innate immune system, restoring epithelial barrier function." (PMID 27058036, 2016). "We describe a patient of refractory Crohn’s disease who developed sarcoidosis and cutaneous vasculitis simultaneously during anti-TNF-α antibody, infliximab, therapy." (PMID 26864464, 2016). "Next, we collected serum samples from anti-TNF-α treatment naive Crohn’s disease patients and measured the serum TNF-α levels by ELISA." (PMID 27150018, 2016). "Indeed, TNF inhibitors carry warnings for increased risk of hematological malignancies in children, adolescents, and young adults, primarily treated for ulcerative colitis or Crohn's disease also treated with immunosuppressant (azathioprine and/or mercaptopurine)." (PMID 28083070, 2016). "We report the first case of esophageal Crohn’s disease successfully treated with tofacitinib in a patient with worsening symptoms despite maintenance therapy with a tumor necrosis factor-α inhibitor." (PMID 27663846, 2016). "IFX, anti-TNF-α antibody, is widely used for refractory Crohn’s disease and there is increasing evidence that it is effective for refractory sarcoidosis." (PMID 26864464, 2016). "Some individuals undergoing anti-TNF-α therapy for Crohn's disease or ulcerative colitis develop psoriasiform lesions." (PMID 27738572, 2016). "The safety risks of using TNF-α inhibitors have also been demonstrated in human studies where patients receiving TNF-α inhibitors for chronic inflammatory disease like RA and Crohn’s disease can develop reactivation of TB disease." (PMID 27822210, 2016). "Infliximab, which is a humanized chimeric monoclonal antibody against TNF-α, is indicated for refractory Crohn’s disease, and several reports have described its effectiveness for refractory sarcoidosis." (PMID 26864464, 2016). "It has been well documented that levels of TNF-α are elevated in serum and intestinal mucosa of patients with IBD with neutralization of TNF-α, the basis of anti-TNF therapy, being associated with improved health, particularly in patients with Crohn's disease." (PMID 25377316, 2015).
Crohn disease (continued). "Despite improvement of medical care and introduction of anti-tumor necrosis factor (TNF) therapy, a substantial number of Crohn disease (CD) patients require bowel resection." (PMID 26559283, 2015). "Anti-tumor necrosis factor antibodies are effective in treating resistant or complicated Crohn’s disease as well as peripheral arthritis." (PMID 26664477, 2015). "We believe the septic knee was as a direct result of intra-abdominal pathology and decided to continue the antibiotic treatment with Imipenem and initiate an anti TNF-alpha agent Adalimumab for the exacerbation of Crohn’s disease." (PMID 26664477, 2015). "The level of TNF-α mRNA in active Crohn’s disease patients was higher than those of the other patients." (PMID 26140540, 2015). "The inflammatory cytokine TNF-α is a central mediator in many immune-mediated diseases, such as Crohn’s disease (CD), spondyloarthritis (SpA) and chronic obstructive pulmonary disease (COPD)." (PMID 26523550, 2015). "We report herein a case of focal non-granulomatous orchitis in a 21-year-old patient with active Crohn’s disease treated by an anti-tumor necrosis factor monoclonal antibody." (PMID 25927973, 2015). "CLDN2 expression can be induced by TNFα and has been reported in various diseases, including Crohn’s disease, ulcerative colitis and celiac disease." (PMID 26589571, 2015). "While anti-TNFα is a recognized treatment of Crohn's disease, its usage is discussed in sarcoidosis." (PMID 24653848, 2014). "While anti-TNFα is a recognized treatment of Crohn's disease, it has been reported to be of clinical use in refractory or severe sarcoidosis." (PMID 24653848, 2014). "Arsenescu and colleagues analysed the expression of RelA, A20, NF‐κB, TNF, IL‐8 and pIgR in mucosal biopsies of 69 Crohn's disease patients and 28 non‐diseased controls." (PMID 24375678, 2014). "Harbouring a deletion of the TNF 3′ AU-rich elements, TNFΔARE/WT mice develop spontaneous ileitis that highly resembles human Crohn's disease." (PMID 25310588, 2014). "We also excluded patients with other inflammatory disease like Crohn ́s disease, because this indication is treated with TNF inhibitors as well." (PMID 26208932, 2014). "The biological agent, tumor necrosis factor alpha (TNFα) inhibitor, has an anti-inflammatory effect and is used when other medical treatment for Crohn’s disease have failed." (PMID 24608416, 2014). "Four months later, a treatment with an anti-TNFα agent, infliximab, was started, because of worsening Crohn's disease recurrences; the dose regimen was 5 mg/Kg every 6 weeks." (PMID 24653848, 2014). "As evidenced by a number of studies, TNF α plays a major role in IBD pathology, and TNF-blocking agents have proven an effective therapy to both ulcerative colitis (UC) and Crohn’s disease (CD)." (PMID 25015298, 2014). "Biologic therapies, such as anti-TNF agents, for Crohn’s disease have provided clinically meaningful improvement in patient reported outcomes while maintaining remission." (PMID 24883246, 2014). "Treatment of Crohn’s disease with an anti-tumor necrosis factor alpha agent (infliximab) successfully induced remission of both the gastrointestinal disease and the oral lesion." (PMID 25433368, 2014). "If anti-TNFα is a recognized treatment of Crohn's disease, its role in sarcoidosis remains discussed." (PMID 24653848, 2014). "Based on these observations, treatments of several chronic inflammatory diseases such as Crohn’s disease, ulcerative colitis, and psoriasis target TNF-α." (PMID 24592264, 2014). "Particularly interesting is TNF-α, a key cytokine in Crohn's disease, also known as cachexin due to its strong appetite suppressing and weight loss inducing effect." (PMID 25147950, 2014). "We report a rare case of steroid resistant Crohn's disease followed by multivisceral sarcoidosis, treated successfully by an anti-TNFα agent, infliximab." (PMID 24653848, 2014).
Crohn disease (continued). "Adalimumab, representing a fully humanised anti-TNF-α antibody, is an established biologic agent in the treatment of Crohn’s disease with proven clinical benefits." (PMID 24400722, 2014). "The expression of syndecan-1 and the proinflammatory cytokine TNFα has been found to be inversely correlated in the colonic mucosa of patients with Crohn's disease." (PMID 23874391, 2013). "Tumor necrosis factor-α (TNF-α) antibodies are currently used in patients with moderate to severe Crohn’s disease (CD) who are unresponsive to conventional therapies." (PMID 24578833, 2013). "We adapted the well-established TNF∆ARE/+ mouse model of Crohn’s disease (which systemically overexpresses TNFα) to generate a homozygous mutant strain that overexpress TNFα only within the intestinal epithelium." (PMID 23977323, 2013). "Infliximab and other tumor necrotizing factor alpha (TNFα) antagonists (adalimumab and certolizumab pegol) are effective treatment options in moderately to severely active Crohn's disease in either remission induction or maintenance therapy." (PMID 24307950, 2013). "He had been treated with infliximab, an anti-TNF-α antibody, for 2 years for Crohn’s disease, and the disease was well controlled." (PMID 23738990, 2013). "This case was unique because of the absence of any history of penetrating ocular trauma and the history of treatment with an anti-TNF-α antibody for Crohn’s disease." (PMID 23738990, 2013). "This case was treated with anti-tumour necrosis factor (TNF)-α antibody for Crohn’s disease before the onset of endophthalmitis." (PMID 23738990, 2013). "The addition of anti-TNF-α antibodies to the therapeutic drugs against Crohn’s disease has been a great innovation in its management." (PMID 27785242, 2013). "Previous experiences of antibody-based therapies for Crohn’s diseased have focused on anti-TNF-alpha antibodies, even if some issues have been raised regarding short- and long-term safety profile of this class of drugs." (PMID 27785242, 2013). "The twenty-first century has brought with it the first biologic agent for Crohn’s disease, infliximab, a monoclonal antibody against tumor necrosis factor alpha (anti-TNFa)." (PMID 23826928, 2013). "Anti-TNF therapies have shown to be effective in the treatment of Crohn's disease and ulcerative colitis, which are both disease of the gastrointestinal tract that are characterized by inflammation." (PMID 23516507, 2013). "Human and animal studies have clearly established tumor necrosis factor (TNF)α as an important mediator of Crohn’s disease pathogenesis." (PMID 23977323, 2013). "Adalimumab is a fully human recombinant IgG1 monoclonal antibody against TNFα which has been approved for rheumatoid arthritis, psoriatic arthritis, ankylosing spondylitis, and Crohn's disease." (PMID 24307950, 2013). "Intestinal interferon-γ and IL-17 mRNA expression was higher in Crohn's disease and remained elevated after anti-TNF-α treatment." (PMID 22778976, 2012). "Limited data have shown a reduction of Crohn’s disease activity during treatment with bupropion, possibly due to TNF decrease, and phenelzine, possibly related to β adrenoreceptor agonism due to NE increase." (PMID 23204981, 2012). "One study in Crohn's disease reported a significant decrease in proinflammatory cytokines (IL-1, IL-6 and TNF-alpha) and one study in ulcerative colitis reported a decrease in IL-6 with HBOT." (PMID 22417628, 2012). "The data assessing anti-TNF agents and wound healing are conflicting and comprise a mixture of small retrospective and prospective studies in RA and a larger study in Crohn's disease." (PMID 23251815, 2012). "One study reported a significant decrease in proinflammatory cytokines (IL-1, IL-6 and TNF-α) after HBOT in 7 patients with Crohn's disease." (PMID 22417628, 2012). "To conclude, the use of a TNF-alpha inhibitor, infliximab, also has been shown to be advantageous for closure ECFs in patients with Crohn’s disease." (PMID 22669399, 2012).